ALB (albumin)
Diseases named in the same sentence as ALB in open-access papers (continued):
Sharing a sentence is not in itself a finding about the gene and the disease.
renal fibrosis (continued). "Ang1-7 supplementation to these mice not only reduced renal mesangial expansion and urinary albumin secretion, but also renal fibrosis and PRAT oxidative stress and inflammation mainly through the attenuation of NOX-mediated ROS production." (PMID 34408726, 2021). "The weight, blood glucose and lipids, 24 h urine albumin and 8-OH-dG, and renal fibrosis were analyzed." (PMID 32090125, 2020). "We found that bFGF treatment significantly alleviate urinary albumin to creatinine ratio and renal fibrosis in db/db mice, suggesting a potential renal protective effect." (PMID 32153399, 2020). "In this study, bFGF treatment can effectively reduce urinary albumin to creatinine ratio and renal fibrosis as well as remodel metabolic phenotype in db/db mice." (PMID 32153399, 2020). "We assessed urinary creatinine and albumin, glomerular volume, renal fibrosis, podocyte number, renal inflammation, oxidative stress, and tissue repair markers (SDF-1 and VEGF) six weeks after the completion of treatment." (PMID 31354913, 2019). "This study demonstrated that low-energy ESWT decreased urinary albumin excretion as well as reduced glomerular hypertrophy and renal fibrosis in the rat model of DN." (PMID 31354913, 2019). "The diabetic animals induced by STZ injection showed decreased serum albumin, elevated kidney/body weight ratio, histological abnormalities, and renal fibrosis." (PMID 28427241, 2017). "Renal injury was examined by albumin reagent kit, and renal fibrosis was examined by Sirius Red staining and Masson's trichrome staining, respectively." (PMID 28427241, 2017). "This is consistent with our recent in vivo studies showing that knockdown of RTN1A attenuated renal fibrosis in albumin overload nephropathy model." (PMID 28336924, 2017). "For this, renal fibrosis and urinary albumin-to-creatinine ratio (ACR), serum creatinine, and blood urea nitrogen (BUN) were evaluated." (PMID 27901066, 2016). "Similarly, in STZ‐induced diabetic rats, ADSC‐Exos administration decreased urinary albumin‐to‐creatinine ratio, suppressed mesangial expansion, and ameliorated renal fibrosis." (PMID 41527491, 2026). "The results indicated that the OV10 group exhibited CKD pathology similar to the TV10 group, with both groups demonstrating significantly higher urinary albumin/creatinine ratio (p < 0.05), tubular injury (p < 0.05), and degree of renal fibrosis (p < 0.05) than the OV8 group." (PMID 39843403, 2025). "Furthermore, irisin decreased urinary albumin excretion and attenuated both renal fibrosis and lipid accumulation." (PMID 36335399, 2022). "Second, a high concentration of albumin in tubular itself may aggravate the damage after administration of CM leading to higher osmotic pressure, severer renal medullary hypoxia and renal fibrosis even worse which was common pathological manifestation of CKD." (PMID 33675474, 2021). "We showed that the combination of EPO and urinary albumin could predict major renal responses more accurately because the percentage of urinary albumin excretion reflected the cause of RI in MM and the level of EPO reflected renal fibrosis." (PMID 32311841, 2020). "Exendin-4 significantly lowered the level of serum triglycerides (TG) and low-density lipoprotein- (LDL-) c, 24 h urine albumin, and 8-OH-dG; improved renal fibrosis and lipid accumulation; and activated renal AMP-activated protein kinase (AMPK) in diabetic mice regardless of BAT excision." (PMID 32090125, 2020). "Considering that our experiments was performed with unconjugated bilirubin and that previous major cohort studies were performed with patient with Gilbert’s syndrome, treatment with albumin-bound bilirubin might have potential benefits for renal fibrosis." (PMID 28225832, 2017).
renal fibrosis (continued). "Our data, showing that albumin-induced miR-184 in cultured tubule cells was associated with reduced LPP3 and abnormal Pai-1 mRNA (both prevented by miR-184 antagomir treatment), suggest a functional link between miR-184 dysregulation and albumin load-induced renal fibrosis." (PMID 28364255, 2017). "Thus, albumin overload by inducing EMT favors renal fibrosis." (PMID 37298591, 2023). "BMMSCs could also reduce tubular EMT and renal fibrosis in albumin-overloaded mice." (PMID 36268508, 2022). "4,27 Therefore, we examined markers of renal fibrosis such as the expression of fibronectin and α-SMA and urinary excretion of albumin, KIM-1, and NGAL 4 weeks after the 2K1C procedure." (PMID 40909559, 2025). "Our study showed that Mudan granules reduced urinary albumin, ameliorated SCr and BUN, and alleviated the pathological renal lesion in rats, suggesting the protective role of Mudan granules in the renal fibrosis of diabetic rats." (PMID 38357745, 2024). "Tubular damage and renal fibrosis have been reported in the AKI experimental model, including the albumin overload strategy." (PMID 34769064, 2021). "Subprofile analysis indicated that COPD patients showed more pronounced deviations in renal functional status (eGFR, serum creatinine, urinary creatinine, albumin/creatinine ratio; N1), while SSc-ILD patients had more marked CT-densitometric indicators of renal fibrosis (N2)." (PMID 41227028, 2025). "Furthermore, except for renal fibrosis, proteinuria is also a pathological feature of CKD, and our results showed that succinate promoted urinary albumin excretion." (PMID 38291510, 2024). "Accordingly, renal fibrosis and function were worsened as revealed by decreased estimated glomerular filtration rate (eGFR) and increased serum BUN, creatinine, β2-microglobulin, 24-hour proteinuria and urine albumin to creatinine ratio (UACR)." (PMID 27145370, 2016). "In our recent study, Smad3 KO in db/db mice were found to be protected from the development of diabetic kidney injury, characterized by the normal levels of urinary albumin excretion and serum creatinine without any evidence for renal fibrosis and inflammation." (PMID 33369170, 2021). "However, the TENE treatment ameliorated renal fibrosis in the BSA-injected diabetic mice without affecting either urine murine albumin or BSA levels." (PMID 31101909, 2019). "Both EV-ADSCs and H-2Kb-ADSCs resulted in reduced kidney/total body weight ratio, blood urea nitrogen (BUN), urine albumin creatinine ratio (uACR), mesangial matrix expansion (MME) and renal fibrosis compared to vehicle alone, without influencing glycemia or survival." (PMID 41597270, 2026).
Shock (60 papers, 2014 to 2026). The state in which profound and widespread reduction of effective tissue perfusion leads first to reversible, and then if prolonged, to irreversible cellular injury. "Albumin administration was associated with improved survival in people with septic shock in a subgroup analysis of the Albumin Italian Outcome Sepsis (ALBIOS) trial." (PMID 41178621, 2026). "In patients with septic shock, the elevation of ischemia-modified albumin was associated with mortality." (PMID 39061994, 2024). "The combination of ischemia-modified albumin and lactate showed good performance in predicting short-term mortality and can be a helpful tool for the early risk stratification of patients with septic shock." (PMID 39061994, 2024). "Albumin experimentally protects against the loss of glycocalyx of the capillary surface in ischemia-reperfusion models, reduces the damage to the glycocalyx, and facilitates its restoration in hemorrhagic shock." (PMID 26136776, 2015). "A valid causal model can then be used to individualize decision making: subgroup analyses showed that treatment efficacy of albumin was better for patients >60 years old, males, and patients with septic shock." (PMID 39899627, 2025). "This study supports previous findings that NAR is a reliable prognostic marker, with ROC curve analysis showing that NAR predicts 90-day mortality in patients with cardiogenic shock more effectively than neutrophil percentage or serum albumin levels alone." (PMID 41357173, 2025). "In septic and septic shock patients admitted to the emergency department, the initial albumin level was found to be the most significant contributor to clinical outcomes." (PMID 38826606, 2024). "The serum lactate and albumin levels in patients with cardiogenic shock are closely related to the severity of their condition and prognosis." (PMID 39624213, 2024). "Meanwhile, we found that septic shock, relapsed/refractory HM, albumin <30g/l, platelets <30×109/l before BSI, and inappropriate empiric antibiotic treatment were independent risk factors for 30-day mortality after BSI in patients with HMs." (PMID 37457950, 2023). "The multicenter, open-label ALBIOS trial found that albumin is a safe alternative to crystalloids, maintains kidney function, and reduces mortality in patients with septic shock." (PMID 37747558, 2023). "The nomogram showed that septic shock, relapsed/refractory HM, albumin <30g/l, platelets <30×109/l before BSI, and inappropriate empiric antibiotic treatment were independent risk factors for 30-day mortality after BSI in patients with HMs." (PMID 37457950, 2023). "The “Early Albumin Resuscitation in Septic Shock” (EARSS) study evaluated early hyper-oncotic albumin use in patients with septic shock." (PMID 38139434, 2023). "In patients with cardiogenic shock, NAR is observed to be a more sensitive diagnostic marker than blood neutrophil or serum albumin level alone." (PMID 35309310, 2022). "Considering patients with septic shock, it has been reported that the lactate/albumin ratio is better than lactate alone in predicting mortality." (PMID 36197158, 2022). "This practice was implemented in our unit after the publication of the results of the ALBIOS trial that showed significant hemodynamic advantages with albumin administration and a possible reduction in mortality in the subgroup of patients with septic shock." (PMID 33251238, 2020). "This study aimed to compare the effects on mortality of albumin and crystalloid, used for fluid resuscitation among adult patients with septic shock, through conducting a meta-analysis and trial sequential analysis (TSA)." (PMID 30570093, 2018). "The impact of albumin on 90-day mortality in patients with septic shock was estimated from five trials, the heterogeneity was determined to be non-significant (P = 0.74, I2 = 0%)." (PMID 25499187, 2014). "Moreover, albumin increases mortality in traumatic brain injury but plays a beneficial role in the treatment of infectious shock." (PMID 41306268, 2025).
Shock (continued). "In the stratification analysis, among septic patients with ALB level ≥27.85 g/L on day 7, a significant reduction in 28-day mortality and incidence of septic shock was displayed in female patients, under 60 years, and in the low-risk subgroup (SOFA score less than 7, APACHE II score less than 19)." (PMID 40438354, 2025). "We find that albumin is beneficial with patient with septic shock consistent with one RCT." (PMID 39899627, 2025). "In this retrospective observational study, factors including a history of CAD, multiple inotrope use, LVEF <40%, lower hemoglobin concentration, albumin infusion, longer CPR attempt, and RRT were identified to be associated with increased in-hospital mortality among patients with cardiogenic shock." (PMID 35321103, 2022). "For the second experiment, higher values of urea, cardiogenic shock, neutrophils, age and SGPT were found to be associated with a higher predicted probability of mortality, while lower values of eosinophils, troponin I, albumin and HCo3a also increased the risk of mortality." (PMID 37072766, 2023). "In addition, fluid losses should be replenished with a supply of albumin, which is a colloid recommended for intravascular volume replenishment, due to reports suggesting a reduction in mortality among patients who were given albumin within 6 h after the diagnosis of septic shock." (PMID 33535608, 2021). "The Albumin Replacement therapy In Septic Shock (ARISS) study will investigate whether maintenance of serum albumin levels of ≥3.0 g/dL with HAS for 28 days improves survival in patients with septic shock when compared with resuscitation and volume maintenance without albumin." (PMID 33925831, 2021). "The combined high-risk category (CD4 < 50 cells/μL and TyG ≥ 9.22) displayed the most severe phenotype, with lower platelet, monocyte, and albumin levels; higher LDH, CRP, and bilirubin concentrations; a mean SOFA score of 6.1; and the highest incidence of septic shock (41.6%)." (PMID 41601726, 2026). "Additionally, a lower incidence of septic shock, multiple organ dysfunction syndrome (MODS), and AKI and a longer duration of ICU-stay days had been observed in patients with ALB level ≥27.85 g/L on day 7, although these differences were not statistically significant between the two groups." (PMID 40438354, 2025). "Although the neutrophil percentage-to-albumin ratio (NPAR) has proven to be a robust systemic inflammation-based predictor of mortality in a wide range of diseases, the prognostic value of the NPAR in critically ill patients with cardiogenic shock (CS) remains unknown." (PMID 33294452, 2020).
bacteremia (59 papers, 2011 to 2026). "Other studies have found low albumin to be associated with poor outcomes in various infections including bacteremia (47, –, 49)." (PMID 39601576, 2025). "This study examined the relationship between C-reactive protein/serum albumin ratio and Q Pitt bacteremia score with all-cause in-hospital mortality in patients with bloodstream infections." (PMID 39252713, 2024). "The relationship between C-reactive protein/albumin ratio and quick Pitt bacteremia score with all-cause in-hospital mortality was determined." (PMID 39252713, 2024). "This study examined the relationship between C-reactive protein/serum albumin ratio and qPitt bacteremia score and all-cause in-hospital mortality in patients with BSIs admitted at an academic, referral hospital in Oman." (PMID 39252713, 2024). "In contrast, increased albumin levels have been correlated with reduced susceptibility to bacteremia in burn patients and used as a marker of infection in the vaginal mucus of pregnant women." (PMID 34154403, 2021). "Low serum levels of albumin along with inappropriate antibiotic therapy are associated with increased 30-day mortality in patients with vancomycin-resistant Enterococcus bacteremia." (PMID 33925831, 2021). "Hospital-acquired bacteremia, polymicrobial bacteremia, and serum albumin of less than 23 g/L were independent risk factors for 30-day mortality rate." (PMID 29479635, 2018). "Mortality rate is high, and hospital-acquired bacteremia, polymicrobial bacteremia, and serum albumin < 23 g/L are associated with increased mortality." (PMID 29479635, 2018). "Previous studies have shown low serum albumin or high serum CRP concentrations to be risk factors for bacteremia in patients with CAP; our findings are consistent with this." (PMID 29382316, 2018). "Older age, being post-transplantation, higher Pittsburgh bacteremia score, and lower level of albumin were identified as independent risk factors for 30-day mortality in patients with MDR A. baumannii complex bacteremia." (PMID 26083415, 2015). "In addition, low total protein and albumin levels were significantly associated with mortality and poor prognostic factors for bacteremia." (PMID 37829654, 2023). "In addition, investigating other risk factors of death from sepsis by pressure injury infections identified hospital-acquired bacteremia, polymicrobial bacteremia, and serum albumin <23 g/L as possible risk factors." (PMID 34442680, 2021). "Hemoglobin, cholesterol, and albumin levels were significantly lower in the bacteremia group, while platelet count, CRP, PCT, glucose, and triglycerides were significantly elevated (all p < 0.05)." (PMID 40792110, 2025). "Laboratory findings demonstrated that patients with complicated bacteremia had lower median albumin levels (3.0 g/dL (IQR 0.9) vs. 3.4 g/dL, P = 0.005) and higher median white blood cell counts (15.1 × 109/L (IQR 13.8) vs. 11.5 × 109/L, P = 0.005)." (PMID 41450351, 2025). "The mean CRP/albumin ratio (8.6 ±1.7) and mean quick Pitt bacteremia score (2.8 ±0.4) were significantly higher in patients with bloodstream infections who died during their hospitalization compared to those who survived." (PMID 39252713, 2024). "Previous studies have highlighted the predictive capability of BUN or the BUN-to-albumin ratio for the mortality rate in bacteremia." (PMID 38673012, 2024). "We have also shown that adding RDW, serum albumin, and lactate scores promotes the risk-predicting performance of MEDS, qSOFA, and NEWS on short-term outcomes of monomicrobial GNB afebrile bacteremia." (PMID 38732284, 2024). "In a study on bacteremia in community-acquired pneumonia, elevated CRP followed by lower plasma albumin was found to predict a higher risk of community-acquired bacteremia." (PMID 37768395, 2023).